LRRC20 (leucine rich repeat containing 20)
Synonyms: FLJ10751; FLJ10844
Tractability: PROTAC: ubiquitination databases record sites on it; its protein half-life has been measured.
Gene: Protein-coding gene on chromosome 10 (70,298,970 to 70,382,650, reverse strand). Ensembl gene ENSG00000172731.
Subcellular location (Human Protein Atlas): Nucleoplasm; Cytosol
Gene Ontology:
Molecular function: protein binding
Genetic constraint (gnomAD): Loss-of-function variants: 11 observed, 15.46 expected, observed/expected ratio (o/e) 0.71, 90% interval 0.45 to 1.18. The upper end of that interval is the gene's LOEUF score, 1.18, which puts it in group 5 of 6, group 1 being the genes least tolerant of losing a copy. Missense variants: 219 observed, 262.85 expected, observed/expected ratio (o/e) 0.83, 90% interval 0.75 to 0.93. Synonymous variants: 121 observed, 111.88 expected, observed/expected ratio (o/e) 1.08, 90% interval 0.93 to 1.26.
Homologues: Orthologues: chimpanzee LRRC20 (100% identical), macaque LRRC20 (99% identical), pig LRRC20 (95% identical), guinea pig LRRC20 (93% identical), rabbit LRRC20 (93% identical), rat Lrrc20 (90% identical), mouse Lrrc20 (90% identical), dog LRRC20 (84% identical), tropical clawed frog lrrc20 (51% identical), zebrafish lrrc20 (42% identical), Drosophila melanogaster Sclp (29% identical), Caenorhabditis elegans K08E7.8 (24% identical).
Diseases named in the same sentence as LRRC20 in open-access papers:
LRRC20 is named in the same sentence as 3 diseases in open-access papers, as found by Europe PMC text mining. Sharing a sentence is not in itself a finding about the gene and the disease. The quoted sentences say what the papers report.
breast carcinoma (1 paper, 2022). "It suggests that upregulated DPP9, LRRC20 and TTBK2 together with downregulated TTC17, ZNF75D and CYTH2 may play pivotal role in the orchestrated adaptive homing of metastatic breast cancer cells in bone niche." (PMID 35685372, 2022).
systemic lupus erythematosus (1 paper, 2022). An autoimmune multi-organ disease typically associated with vasculopathy and autoantibody production. "LRRC20 was reported to correlate with disease manifestations and severity of systemic lupus erythematosus (SLE)." (PMID 35685372, 2022).
tumor (2 papers, 2021 to 2022). "From our analyses, DPP9 (Dipeptidyl Peptidase 9), LRRC20 and TTBK2 expressions were the top three upregulated genes that may be associated with the homing of the migrated tumour cells in the bone." (PMID 35685372, 2022).